BTK (Bruton tyrosine kinase)
Diseases named in the same sentence as BTK in open-access papers (continued):
Sharing a sentence is not in itself a finding about the gene and the disease.
autoimmune disease (continued). "Therefore, grasping the structural data about the function of BTK is vital for designing inhibitors targeting BTK for B-cell malignancy, autoimmune diseases, and COVID-19 therapy." (PMID 36986499, 2023). "Given its central function in B-cell receptor signaling, inhibition of BTK is an attractive approach for the treatment of a wide variety of autoimmune diseases that involve aberrant B-cell function including systemic lupus erythematosus (SLE), rheumatoid arthritis (RA), and multiple sclerosis (MS)." (PMID 36294458, 2022). "RA is another B-cell-mediated autoimmune disease where inhibiting BTK in macrophages and B cells may be a promising therapeutic target for RA." (PMID 36294458, 2022). "Of note, BTK inhibitor share a variety of clinical applications, ranging from treatment of B cell malignancies, to autoimmune diseases and COVID-19, which raise the question on whether TBBPA may interfere with these therapeutic actions." (PMID 36386828, 2022). "Ibrutinib, the first orally available BTK selective inhibitor, is approved for the treatment of various B-cell malignancies and is now being studied in pre-clinical and clinical trials examining its anti-inflammatory effect in autoimmune diseases." (PMID 36521376, 2022). "Bruton’s tyrosine kinase (BTK) inhibitors, which are currently first-line treatments for chronic lymphocytic leukemia, represent an emerging class of compounds for the treatment of autoimmune diseases." (PMID 35852869, 2022). "In addition, due its immunomodulatory effect, ibrutinib was approved by the FDA in treating the steroid-resistant chronic graft-versus-host disease (GVHD); more studies are ongoing to use the BTK inhibitors to address other autoimmune disorders." (PMID 35631621, 2022). "Therefore, if their efficacy in autoimmune diseases is proven by ongoing trials, BTK inhibitors will significantly enrich the treatment options for patients with autoimmune diseases, especially given the possibility of various combination therapies." (PMID 34778053, 2021). "Such ongoing clinical studies and preclinical evidence demonstrate the immunosuppressive effects of BTK inhibitors in autoimmune diseases and warrant further considerations of new clinical trials on BTK inhibitors as therapeutic agents for these autoimmune diseases." (PMID 34778053, 2021). "While autoimmune diseases with autoantibody driven pathology mechanisms appear to be amenable to therapeutic intervention by BTK inhibitors, correlation of autoantibody threshold levels to clinical efficacy has not been published or well established in these studies." (PMID 34803999, 2021). "Continuing the hypothesis that CXCL12 is a driver of autoimmune diseases, a multi targeted approach for inhibiting BTK and other kinases could have beneficial effects." (PMID 34803999, 2021). "Poseltinib showed a probability as novel BTK inhibitor for treatment of autoimmune diseases." (PMID 34548595, 2021). "In summary, BTK has become an important target for inflammatory and autoimmune disorders." (PMID 34443496, 2021). "Additionally, experimental models of human autoimmune diseases have revealed that BTK is a target of the utmost importance to cancel B cell pro-inflammatory functions without the risks associated with cell depletion." (PMID 34685540, 2021). "Bruton’s tyrosine kinase (BTK) represented, in the past ten years, an important target for the development of new therapeutic agents that could be useful for cancer and autoimmune disorders." (PMID 34885993, 2021). "Furthermore, other BTK inhibitors are under evaluation for the treatment of autoimmune diseases in which BTK has known functions." (PMID 34264564, 2021). "Poseltinib was confirmed as a potential BTK inhibitor for the treatment of autoimmune diseases." (PMID 34548595, 2021). "Therefore, BTK has become a new therapeutic target for a group of hematologic and autoimmune disorders." (PMID 34447768, 2021).
autoimmune disease (continued). "Based on the data collected in this study, we propose that current compound characteristics of BTK inhibitor drug candidates for the treatment of autoimmune diseases have achieved the selectivity, safety, and coverage requirements necessary to deliver therapeutic benefit." (PMID 34803999, 2021). "BTK has become an important pharmacological target due to its essential role downstream of immune receptors; for example, increased receptor signaling increases BTK activity driving multiple B-cell malignancies, autoimmune diseases, and allergies." (PMID 33226337, 2020). "Indeed, transgenic mice overexpressing BTK in B cells manifested SLE-like autoimmune disease involving kidneys, lungs, and salivary glands." (PMID 29706952, 2018). "Bruton’s tyrosine kinase (BTK) is a key kinase in the B-cell surface antigen (BCR) signaling pathway, which plays an important role in B-cell growth, development, and differentiation, aberrant BTK function is thought to be associated with cancer and autoimmune diseases." (PMID 38381215, 2024). "Therefore, BTK inhibitors represent a promising therapeutic strategy for autoimmune diseases." (PMID 38698867, 2024). "Thus, the depletion of BTK activity shall be helpful in the prognosis of autoimmune diseases." (PMID 36986499, 2023). "In addition, enhanced BTK activity is correlated with autoimmune disease." (PMID 36903645, 2023). "BTK is not reported to have genetic evidence linking it with the autoimmune disorders being clinically tested with BTK inhibitors, but functional signaling pathways associated with clinical pathology have individual proteins that themselves interact with signaling pathways connecting to BTK." (PMID 34803999, 2021). "To date, five compounds, able to block BTK in an irreversible manner, have been launched in the market, whereas many reversible BTK inhibitors (BTKIs), with reduced side effects that are more useful for long-term administration in autoimmune disorders, are under clinical investigation." (PMID 34885993, 2021). "Our results demonstrate an unexpected role of BTK in optimal T-cell activation and in the pathogenesis of autoimmune aplastic anemia, providing insights into the molecular regulation of T-cell activation and the pathogenesis of T-cell-mediated autoimmune disease." (PMID 31431692, 2020). "Targeting BTK using ibrutinib may be an interesting approach to treat autoimmune diseases." (PMID 29706952, 2018). "BTK is required for synergistic cytokine response by TLR9 and BCR in human and murine B cells, with implications in B cell activation and autoimmune diseases." (PMID 40980882, 2025). "•Bruton Tyrosine Kinase (BTK) plays an important role in several immunological pathways; hence, they are potential treatments for certain autoimmune disorders." (PMID 38125430, 2023). "Irrespective of their mode of action, the efficacy of BTK inhibitors such as evobrutinib at least partly relies on how BTK in B and myeloid cells is regulated and triggers pathogenic subsets, which may differ between autoimmune diseases." (PMID 35852869, 2022). "Three additional autoimmune diseases, PV, ITP, CSU as well as two inflammatory immune-mediated diseases, GVHD and asthma, were diseases where two or fewer BTK inhibitors in clinical trials were tested." (PMID 34803999, 2021). "Taken together with the in vivo work using the PCI-32765 BTK inhibitor this work demonstrates that targeting BTK provides a valid therapeutic approach to treat SLE and other autoimmune diseases." (PMID 23967355, 2013). "This review summarizes preclinical and clinical development of ibrutinib and other novel BTK inhibitors (GDC-0834, CGI-560, CGI-1746, HM-71224, CC-292, and ONO-4059, CNX-774, LFM-A13) in the treatment of B-cell malignancies and autoimmune disorders." (PMID 23958373, 2013). "Such inhibition of BTK with PCI-32765 has recently been shown to be efficacious in patients with B cell malignancies as well as in mice with autoimmune diseases." (PMID 23136880, 2012).
autoimmune disease (continued). "As a result of blocking BTK signaling, BTK inhibitors can potentially affect autoimmune diseases involving B cells and non-B cells." (PMID 40385351, 2025). "So far, no BTK inhibitors have been approved by the EMA or FDA for autoimmune diseases such as MS or RA." (PMID 40676697, 2025). "Given BTK’s key involvement in BCR signaling, its inhibition presents an attractive therapeutic approach for autoimmune diseases involving abnormal B cell function, such as rheumatoid arthritis (RA), systemic lupus erythematosus (SLE), or multiple sclerosis (MS)." (PMID 39518015, 2024). "Combining these therapies with B cell-modulating agents, such as anti-CD20 antibodies or Bruton tyrosine kinase (BTK) inhibitors, may represent the next step in the evolution of these treatments, conferring multimodal activity for complex autoimmune diseases." (PMID 39697333, 2024). "Bruton’s tyrosine kinase (BTK), a crucial regulator of B cell development, proliferation, activation, and differentiation, has become a focal point for therapies targeting B cell malignancies and autoimmune diseases." (PMID 39676874, 2024). "The novel, highly selective, central nervous system-penetrating, irreversible BTK inhibitor evobrutinib strongly suppresses BCR- and Fc receptor-mediated signaling, which makes it a promising agent in the treatment of RA, MS, and other autoimmune diseases." (PMID 36903645, 2023). "Resistance to covalent inhibitors, their adverse effects, and the void in approved BTK inhibitors for autoimmune diseases paved the way for the discovery of non-covalent inhibitors of BTK." (PMID 36986499, 2023). "Taken together, the BTK mediated BCR and TLR interactions may play a crucial role in autoimmune diseases." (PMID 36521376, 2022). "BTK influences the production of messenger molecules, which can abnormally activate the BCR signaling pathway and transform B cells into self-reactive B cells responsible for autoimmune diseases." (PMID 35628931, 2022). "Bruton’s tyrosine kinase (BTK) is an essential protein in B-cell antigen receptor (BCR) signaling pathway and is known to be related to pathogenetic effect on B-cell related malignancies and various autoimmune diseases." (PMID 36521376, 2022). "The aberrant activation of B cells and innate immunity plays a central role in the pathogenesis of autoimmune diseases and inflammation, and given the central role of BTK in BCR and FcR signaling pathways, BTK inhibition is a promising target for immunomodulatory therapy." (PMID 35631621, 2022). "SLE and SJ are two autoimmune diseases where BTK inhibition is not providing therapeutic benefit despite the presence of B cells in the associated pathology." (PMID 34803999, 2021). "Although ibrutinib has not been studied clinically as a BTK inhibitor in MS, it has shown efficacy in other autoimmune diseases, such as arthritis, lupus, and recently in treatment of COVID-19 (SARS-CoV-2)." (PMID 39355638, 2021). "Several BTK inhibitors including evobrutinib, spebrutinib, branebrutinib, 298 and HM71224299 have been assessed in clinical trials for the treatment of autoimmune diseases, such as rheumatoid arthritis, systemic lupus erythaematosus, and remitting multiple sclerosis." (PMID 34054126, 2021). "Recently Bruton’s tyrosine kinase (BTK), a crucial terminal kinase enzyme in the B-cell antigen receptor (BCR) signaling pathway, has emerged as an attractive target for therapeutic intervention in human malignancies and autoimmune disorders." (PMID 23958373, 2013). "However, the clinical success rate for BTK inhibitors in RA has been relatively poor compared to the promising results of BAFF and APRIL-targeted therapies, which have generally shown better efficacy across multiple autoimmune diseases." (PMID 40821822, 2025).
autoimmune disease (continued). "BTKi can selectively inhibit BTK activity, and it intervenes in B-cell development by regulating the BCR signaling pathway to control the further development of various B-cell malignant diseases, and regulates the FcγR signaling pathway to treat autoimmune diseases." (PMID 40959072, 2025). "To date, no data has been reported for BTK inhibitors currently in autoimmune disease clinical trials regarding the effects of BTK cysteine 481 mutations on drug efficacy or whether such mutations are common in the autoimmune diseases studied with these drugs." (PMID 34803999, 2021). "Importantly, BTK can modulate signaling, acting as a “rheostat” rather than an “on-off” switch; thus, overexpression leads to autoimmunity while decreased levels improve autoimmune disease outcomes." (PMID 36294458, 2022). "Due to potential off-target effects, irreversible covalent BTK inhibitors, such as ibrutinib, are not approved by FDA for long-term treatment of autoimmune disorders." (PMID 33627128, 2021). "The genetic correlations of RA, MS, and SLE biomarkers with members of the TEC family were analyzed, and the results indicated that BTK and members of the TEC family may not be disease drivers, but they are part of signaling pathways engaged in the pathophysiology of autoimmune disorders." (PMID 36903645, 2023). "Noncovalent BTK inhibitors such as pirtobrutinib (LOXO-305), MK-1026 (ARQ-531), fenebrutinib (GDC-0853), and vecabrutinib (SNS-062) also look promising in oncology clinical trials and may similarly be candidates for treating autoimmune diseases." (PMID 34803999, 2021).
Waldenström macroglobulinemia (75 papers, 2016 to 2026). "BTK inhibitors are well recognized for their effectiveness in treating Waldenstrom macroglobulinemia with MyD88 mutation." (PMID 38765016, 2024). "Approximately 93–97% of patients with Waldenstrom macroglobulinemia have a somatic mutation in MyD88, which triggers tumor growth by activating NF-κB signaling via BTK." (PMID 38765016, 2024). "The prevalence of the somatic MYD88 L265P mutation is over 90% in patients with Waldenstrom macroglobulinemia (WM), and the Bruton tyrosine kinase (BTK) pathway plays an essential role in the signaling of mutated MYD88 providing survival advantage and proapoptotic mechanisms to malignant WM cells." (PMID 36051045, 2022). "Here, we describe a case of a patient who developed Bing Neel syndrome as a secondary complication of Waldenström's macroglobulinemia and exhibited a remarkable response to Zanubrutinib, a second‐generation Bruton tyrosine kinase (BTK) inhibitor." (PMID 41341565, 2025). "Bruton’s tyrosine kinase (BTK) inhibition is one of the treatment standards for patients with relapsed/refractory Waldenström’s macroglobulinemia (WM) and for patients with WM who are unsuitable for immunochemotherapy (ICT)." (PMID 36402930, 2023). "Tirabrutinib is a highly selective BTK inhibitor that has been newly utilized in treating primary lymphoma of the central nervous system, Waldenstrom macroglobulinemia, and plasma cell lymphoma." (PMID 38125430, 2023). "Regarding different BTK inhibitors, a phase 3 study demonstrated that the incidence and severity of BTK inhibitor toxicities were lower with zanubrutinib than ibrutinib in Waldenström macroglobulinemia." (PMID 36505470, 2022). "The hematopoietic cell kinase (HCK) regulates BTK activation and represents a potential therapeutic target in Waldenstrom macroglobulinemia (WM)." (PMID 36051045, 2022). "The use of Bruton Tyrosine Kinase (BTK) inhibitors in Waldenström’s Macroglobulinemia (WM) is evolving." (PMID 35950210, 2022). "Zanubrutinib (BGB-3111), a next-generation BTK inhibitor with minimal off-target effects, has demonstrated higher efficacy and safety for treating Waldenström macroglobulinemia, compared with ibrutinib." (PMID 36505470, 2022). "Active third-line therapies in Waldenström macroglobulinemia will include second-generation BTK inhibitors, purine nucleoside analogs, everolimus, and lenalidomide." (PMID 29712895, 2018). "Notably, activation of BTK signaling is an essential feature of some B-cell malignancies such as chronic lymphoid leukemia (CLL) and Waldenstrom’s macroglobulinemia (WM), and inhibitors of BTK (i.e., ibrutinib) are standard of care therapies for these cancers." (PMID 40232347, 2025). "Recently, KIN-8194, a dual inhibitor of BTK (IC50 = 0.915 nM) and HCK (IC50 < 0.495 nM), was shown to potently affect the survival of ABC-type DLBCL and Waldenström Macroglobulinemia with a pathogenic Myd88-L265P mutation, while minimally affecting healthy B-cells." (PMID 38454120, 2024). "However, complete response rates with single-agent BTK inhibitors in Waldenström’s Macroglobulinemia are low suggesting that alternative survival signaling pathways in WM cells remain activated in patients treated with BTK inhibitors." (PMID 37954584, 2023). "Ibrutinib, a first‐generation Bruton's tyrosine kinase (BTK) inhibitor, is now considered a standard treatment for patients diagnosed with Waldenström macroglobulinemia (WM)." (PMID 41341565, 2025). "Orelabrutinib, as a second-generation BTK inhibitor, has demonstrated potential efficacy in the treatment of CLL/SLL, MCL, and relapsed or refractory Waldenström's macroglobulinemia." (PMID 37925380, 2023). "In this BCR pathway, BTK plays a major role and can be targeted by BTK inhibitors (BTKi), already used in CLL, MCL, MZL, Waldenström macroglobulinemia, and DLBCL-ABC." (PMID 36620555, 2022).
Waldenström macroglobulinemia (continued). "Ibrutinib is a first-in-class oral irreversible inhibitor of Bruton Tyrosine Kinase (BTK), a critical enzyme in the B-cell receptor signaling cascade, and is highly effective in the treatment of CLL, MCL and Waldenstrom’s macroglobulinaemia." (PMID 36304465, 2022). "Ibrutinib, an oral irreversible BTK inhibitor, covalently binds the 481 cysteine of the kinase domain, blocking BTK activity but not interactions with Syk, and has been approved in 2016 for treatment of CLL, MCL, and Waldenström’s macroglobulinemia." (PMID 33322351, 2020).